OVOL2 (ovo like zinc finger 2)
Diseases named in the same sentence as OVOL2 in open-access papers (continued):
Sharing a sentence is not in itself a finding about the gene and the disease.
colorectal tumor (1 paper, 2023). "OVOL2 is a bivalent gene and a colorectal tumor suppressor gene which inhibits the colorectal tumor progression and metastasis." (PMID 37138231, 2023).
diabetes (1 paper, 2021). "Conversely, we did not measure any change in the expression of any β-cell-specific genes following Ovol2 inactivation in both MIN6 and EndoC-bH1 cells, indicating that impaired epithelial gene expression is insufficient to trigger β-cell dedifferentiation in diabetes." (PMID 33989778, 2021).
dilated cardiomyopathies (1 paper, 2024). "In addition to known associations, our analysis also identified novel regulators, including the identification of TFs FPM315 and OVOL2, which are implicated in dilated cardiomyopathies, and TEAD1 and TEAD2 in both dilated and ischemic cardiomyopathies." (PMID 38673810, 2024).
hair loss (1 paper, 2025). "Therefore, OVOL1 and OVOL2 may represent potential therapeutic targets for the treatment of hair loss." (PMID 40671824, 2025).
lymphopenia (1 paper, 2023). Reduction in the number of lymphocytes. "A viable missense allele (C120Y) of Ovol2, expressed ubiquitously or specifically in TECs, results in lymphopenia, in which T cell development is compromised by loss of medullary TECs and dysfunction of cortical TECs." (PMID 38012144, 2023). "OVOL2 expression changes should be considered in cases of unexplained thymic hypoplasia and lymphopenia." (PMID 38012144, 2023).
Macular dystrophy (1 paper, 2024). Macular dystrophy is a nonspecific term for retinal degeneration, generally confined to the macula, usually presumed of genetic origin. "The heterozygous c.701A>T/p.Asn234Ile of OVOL2 was identified in a patient diagnosed with macular dystrophy (Case wy5)." (PMID 38785568, 2024).
non-small cell lung carcinoma (1 paper, 2022). A group of at least three distinct histological types of lung cancer, including non-small cell squamous cell carcinoma, adenocarcinoma, and large cell carcinoma. "Western blotting was used to determine the expression of OVOL2 in different non-small cell lung cancer (NSCLC) cell lines and mouse models." (PMID 35346238, 2022).
skin tumors (1 paper, 2020). "However, the expression of OVOL1 and OVOL2 as well as their functions in skin neoplasms are poorly understood." (PMID 32106476, 2020). "Ovo-like transcriptional repressor 1 (OVOL1) and ovo-like zinc finger 2 (OVOL2) are important modulators of EMT in some tumors, but their roles in skin tumors remain elusive." (PMID 32106476, 2020).
thyroid cancer (1 paper, 2022). "Gene expression analysis in thyroid cancer patients and cell lines showed that OVOL2 is mainly associated with epithelial features and its expression is deeply impaired in ATC." (PMID 35337349, 2022). "We analyzed the Thyroid Cancer (THCA) gene expression dataset of The Cancer Genome Atlas (TCGA) project to evaluate OVOL2 expression and its potential correlation with EMT features in thyroid cancer." (PMID 35337349, 2022).
cancer (24 papers, 2013 to 2025). A tumor composed of atypical neoplastic, often pleomorphic cells that invade other tissues. "In cancer, OVOL2 loss of function has been reported in many settings and often associated with high aggressiveness and poor patients’ outcome." (PMID 35337349, 2022). "The CD133 signature genes included PROM1, which encoded CD133 molecules (“CD133-up”), and OVOL2, whose encoded transcription factors have been previously implicated in epithelial differentiation and cancer progression (“CD133-down”)." (PMID 30717708, 2019). "We hypothesized that OVOL2 may regulate aerobic glycolysis, a hallmark of cancer, to maintain NSCLC cell survival." (PMID 35346238, 2022). "OVOL2 loss in some types of cancers is linked to aggressiveness and poor prognosis." (PMID 35337349, 2022). "Moreover, we identify TGF-β signaling as another target that OVOL2 antagonizes, suggesting that targeting signaling pathways may be one general mechanism underlying OVOL2's anti-cancer functions." (PMID 28455959, 2017). "OVOL2 can inhibit epithelial‐to‐mesenchymal transition and cancer cell migration, invasion, and metastasis." (PMID 35896951, 2022). "Future work will focus on the identification of the E3 ubiquitin ligase and the development of related inhibitors to improve the protein expression of OVOL2 in cancer cells and hence inhibit NF-κB pathway." (PMID 35346238, 2022). "While ectopic expression of OVOL2 significantly inhibited aerobic glycolysis, simultaneous activation of NF-κB signaling by overexpression of P65 completely abolished the inhibitory effects of OVOL2 on glucose uptake and lactate production in cancer cells." (PMID 35346238, 2022). "Immunoprecipitation with an anti-OVOL2 antibody also pulled down P65, suggesting that OVOL2 is typically present in a complex with P65 in cancer cells." (PMID 35346238, 2022). "Conversely, we examined the effect of OVOL2 KO on cancer cell proliferation and ATP levels using a galactose or glucose‐containing medium." (PMID 35896951, 2022). "Similar to the results of OVOL2 modulation of cancer cell proliferation via NCoR, OVOL2 regulated the invasion of MDA‐MB‐231 and MCF7 cells in an NCoR‐dependent manner." (PMID 35896951, 2022). "Overall, these data suggested that OVOL2 regulates glycolysis and cancer cell proliferation under hypoxic conditions." (PMID 35896951, 2022). "Using different cancer cell lines, OVOL2 KO MEFs, OVOL2 conditional KO mice and tumor specimens, we revealed that OVOL2 modulated glycolytic gene expression, glucose uptake and lactate production." (PMID 35896951, 2022). "Given that OVOL2 is down‐regulated in cancer, correlates with clinical outcomes and represses glycolysis, OVOL2 is expected to be a promising target for cancer therapy." (PMID 35896951, 2022). "Intriguingly, it has been shown that both Ovol2 and Zeb2 modulate cellular plasticity by fine-tuning the hybrid epithelial/mesenchymal states of Cd44+ cancer cells." (PMID 33989778, 2021). "It is reported that the TFs OVOL1 and OVOL2 play critical roles in inducing the transition from mesenchymal to epithelial (MET) in several types of human cancers." (PMID 27765529, 2017). "Consistent with previous reports that EMT promotes stemness, the expression of a well-known cancer stem cell marker CD44 decreased upon Ovol2-induced transition to E and increased upon Zeb1/Snail-induced transition to M." (PMID 26554584, 2015). "Using two models of prostate and breast cancer mesenchymal cells, we discovered that TFs OVOL1 (OVO-like 1, Entrez Gene ID 5017) and OVOL2 (Gene ID 58495) are associated with MET in our models, as well as in other cancers." (PMID 24124593, 2013). "Inhibiting OVOL2 in LSD1 KO cells restored the cancer stem cell phenotype of HCT116 cells." (PMID 37138231, 2023). "Furthermore, LSD1, the demethylase of H3K4me1, promotes cancer cell proliferation and migration through inhibiting the expression of OVOL2 via regulating the histone modification level of its promoter CGI." (PMID 37138231, 2023).
cancer (continued). "Knockdown of OVOL2 in LSD1 knockout HCT116 cells restored the cancer cell phenotype." (PMID 37138231, 2023). "Many studies indicate a fundamental role of OVOL2 in cancer, where it inhibits EMT and metastasis by suppressing ZEB1 expression in breast cancer and nasopharyngeal carcinoma, TWIST in lung cancer, c-Myc in cutaneous squamous cell carcinoma, and Wnt signaling in colorectal cancer." (PMID 35337349, 2022). "Importantly, NCoR KD almost completely abolished the ability of OVOL2 to inhibit cancer cell proliferation, suggesting that OVOL2 primarily regulates cancer cell proliferation through NCoR." (PMID 35896951, 2022). "Similar to OVOL2 KO cancer cells, OVOL2 KO MEFs exhibited enhanced glycolytic gene expression." (PMID 35896951, 2022). "OVOL2 can inhibit cancer cell migration, invasion, and metastasis." (PMID 35896951, 2022). "Moreover, hypoxia increased cancer cell proliferation, and OVOL2 overexpression almost completely abrogated hypoxia‐stimulated cancer cell proliferation, suggesting a key role for OVOL2 in inhibiting hypoxia‐induced cancer cell proliferation." (PMID 35896951, 2022). "Meanwhile, OVOL1 and OVOL2 are considered critical inducers of EMT/MET in human cancers." (PMID 32106476, 2020). "Furthermore, OVOL1 and OVOL2 are co-expressed in multiple cancer cell lines and they induce similar gene expression profiles consistent with MET, which indicate analogous functions." (PMID 24124593, 2013). "Consequently, a greater knockdown of OVOL1 and OVOL2 would induce a more complete EMT transformation in cancer cells." (PMID 24124593, 2013). "Furthermore, this analysis identified the same set of genes to correlate positively with either OVOL1 or OVOL2 expression (r > 0.5) in 917 cancer cell lines." (PMID 24124593, 2013). "Mechanismly, IGFBP7 was highly expressed in cancer-associated fibroblasts (CAF) and mesenchymal cells, and was induced by epithelial-to-mesenchymal transition (EMT) signaling, since its expression was increased by TGF-beta treatment and reduced by overexpression of OVOL2 in GC." (PMID 36681667, 2023). "This evidence underscored a previously unknown function of OVOL2 in cancer." (PMID 35337349, 2022). "Indeed, some works reported an association of OVOL2 with inhibition of cancer cells' proliferation, but no mechanistic details or functional validation have been provided so far." (PMID 35337349, 2022). "As OVOL2 regulates aerobic glycolysis in an NCoR‐dependent manner and glycolysis plays an important role in modulating cancer cell proliferation, invasion, and metastasis, we first examined whether OVOL2 modulates cancer cell proliferation through NCoR in cells cultured on regular medium." (PMID 35896951, 2022). "The role of TFCP2L1 in driving expression of epithelial genes was reinforced by analyses of the Cancer Cell Line Encyclopaedia (CCLE) showing positive correlation between TFCP2L1 (and also OVOL2) and EPCAM." (PMID 37236926, 2023). "Mechanistically, knockout of LSD1 upregulates the transcription of bivalent genes, such as OVOL2, via modifying the H3K4 methylation at promoter regions to inhibit the growth and metastasis of cancer cells." (PMID 37138231, 2023). "OVOL2, an inhibitory C2H2 zinc finger transcription factor, is a potential tumor suppressor in cancers." (PMID 35346238, 2022). "Taken together, these data demonstrate that OVOL2 is downregulated in NSCLC and can impair the survival of cancer cells." (PMID 35346238, 2022). "However, whether OVOL2 regulates cancer metabolism remains unclear." (PMID 35896951, 2022). "Therefore, OVOL2 could serve as a prognostic indicator for cancer patients." (PMID 32089740, 2020). "We demonstrate a novel function of two TFs, OVOL1 and OVOL2, as critical inducers of MET in human cancers." (PMID 24124593, 2013).
cancer (continued). "To test the roles of OVOL-TFs in MET, as well as the potential function of OVOL2 as a transcriptional repressor of ZEB1, we correlated our RNA-seq results with gene expression in multiple cancer cell lines (Barretina study)." (PMID 24124593, 2013). "Our study shows that the ESRPs are regulated by the OVOLs in mesenchymal cancer cells, and that their expression correlates with the OVOLs in the Barretina study: r = 0.76 with OVOL1 and r > 0.81 with OVOL2." (PMID 24124593, 2013). "Since GLUT1 mediates glucose import across the cell membrane, which is the first step of glycolytic metabolism in cancer cells, we next sought to determine whether GLUT1 is involved in OVOL2-regulated glycolysis inhibition." (PMID 35346238, 2022). "OVOL2 is downregulated in NSCLC and overexpression of OVOL2 inhibits the survival of cancer cells." (PMID 35346238, 2022). "Therefore, TGF-β signaling releases the suppression by OVOL2; once the TGF-β output level reaches a threshold level that is sufficient to induce the EMT, cancer invasion and metastasis occur." (PMID 28455959, 2017). "In addition, the 917 cancer cell-lines in the Barretina study show high correlation between the expression of OVOL1 and OVOL2 (r = 0.76)." (PMID 24124593, 2013). "Interestingly, these TFs, together with OVOL1/2 (Ovo Like Transcriptional Repressors 1 and 2), had previously been suspected to inhibit epithelial–mesenchymal transition in cancer cells with a hierarchically dominant position for GRHL2, which directly induces expression of EHF and OVOL2." (PMID 41385584, 2025). "Therefore, the relatively high levels of CDH3, OVOL2, and GRHL2 in patients with poor survival might highlight the role of hybrid E/M phenotype in metastatic progression, at least in these carcinomas." (PMID 27008704, 2016).
tumor (16 papers, 2017 to 2025). "Overall, these data suggested that OVOL2 modulates tumor growth and metastasis mainly through NCoR‐dependent glycolysis." (PMID 35896951, 2022). "OVOL2 directly inhibits the expression of several key glycolytic genes that facilitate aerobic glycolysis, tumor growth, and metastasis." (PMID 35896951, 2022). "Many studies have shown that Ovol2 is closely related to epithelial–mesenchymal transition (EMT) during tumor invasion." (PMID 35346238, 2022). "OVOL2 effects on cytoskeleton dynamics concurrently impact on two fundamental processes guiding tumor cell biology: EMT and cell cycle regulation." (PMID 35337349, 2022). "However, the association between OVOL2 and tumor energy metabolism is unknown." (PMID 35346238, 2022). "NCoR KD almost abrogated the ability of OVOL2 to suppress tumor growth and metastasis, indicating that OVOL2 regulates tumor growth and metastasis predominantly through NCoR." (PMID 35896951, 2022). "Our findings that OVOL2 suppresses TS cell proliferation are consistent with the known tumor suppressor functions of OVOL2 in other cell types." (PMID 32244352, 2020). "In the NSMP subtype, the non-inflamed phenotypes were characterized by elevated expression of OVOL2, a potential tumor suppressor gene, However, the role of OVOL2 in tumor immunity remains unclear." (PMID 39751650, 2025). "Additionally, OVOL2 deletion significantly reduced the median survival time and life expectancy of tumor‐bearing PyVT‐Ovol2KO mice." (PMID 38627980, 2024). "The loss of OVOL2 promotes fatty acid oxidation (FAO), providing additional energy and NADPH to sustain stemness characteristics, including sphere‐forming capacity and tumor initiation." (PMID 38627980, 2024). "OVOL2 loss enhances fatty acid oxidation (FAO), fueling stemness traits and tumor initiation." (PMID 38627980, 2024). "However, when GLUT1 was knocked down, tumor growth promoted by P65 overexpression or OVOL2 knockdown was obviously suppressed." (PMID 35346238, 2022). "Similarly, reexpression of OVOL2 significantly rescued the tumor growth phenotype driven by P65 overexpression in NCI-H1299 cells." (PMID 35346238, 2022). "Its down-regulation, mediated by OVOL2, could mildly affect tumor cells but may have a relevant effect on tumor vascularization, which could not be appreciated by the in vitro approaches we used." (PMID 35337349, 2022). "Interestingly, individual OvoL2 isoforms in mice display strikingly different effects when expressed in patient‐derived xenografts, only the OvoL2 repressor can inhibit tumor progression." (PMID 33372708, 2021). "Given that OVOL1/2 inhibited the expression of EMT-related factors such as vimentin and ZEB1, we hypothesized that knockdown of OVOL1 or OVOL2 may enhance tumor cell invasion." (PMID 32106476, 2020). "However, the underlying molecular mechanism and the association between OVOL2 and tumor progression has not been systematically elucidated." (PMID 28455959, 2017). "In a mouse model, OVOL2 deletion resulted in enhanced FAO capability, increased tumor‐initiating capacity, and accelerated tumor growth." (PMID 38627980, 2024). "Perhaps developing drugs to reactivate the expression of OVOL2 and thus induce MET in tumour cells would be an excellent option for anti‐metastasis." (PMID 36808651, 2023). "In the present study, we aimed to investigate the clinical relevance of NF-κB signaling and OVOL2 and examine their regulatory features in NSCLC cells and mouse tumor models." (PMID 35346238, 2022). "Using human clinical tumor samples and a human SCC cell line, we found that the OVOL2/ZEB1 axis was crucially involved in the development of cSCC." (PMID 32106476, 2020).
tumor (continued). "Because OVOL2 inhibits TGF-β-induced EMT and tumor metastasis, we predicted that TGF-β signaling is directly repressed by OVOL2." (PMID 28455959, 2017). "Ovo Like Zinc Finger 2 (OVOL2) is involved in embryo development and adult tissue homeostasis and regulates tumor growth and metastasis, promoting EMT while inhibiting autophagy; alters the expression of inflammation-related factors; and organizes a regulatory network to control energy homeostasis." (PMID 41440381, 2025). "In addition, similar to OVOL2‐overexpression, knockdown of CPT1A inhibited tumor initiation in MDA‐MB‐231 xenografts in nude mice." (PMID 38627980, 2024). "The metastatic tumor cells easily adapt to the new conditions in a specific tissue, which is controlled by “phenotypic stability factors” (e.g., grainy head-like 2 (GRHL2), ovo-like zinc finger 2 (OVOL2), DNp63a, NUMB, etc.)that balance such hybrid phenotypes." (PMID 38252319, 2024). "In addition, we assayed the in vivo tumor‐initiating capacity (TIC) of limiting dilutions of MDA‐MB‐231 cells with or without OVOL2 overexpression." (PMID 38627980, 2024). "We found that OVOL2 knockout alone did not induce tumor development." (PMID 38627980, 2024). "Besides, perhexiline, a CPT1 inhibitor used clinically for antianginal treatment, significantly inhibited tumor initiation and promoted mice survival in OVOL2 KO mice not in OVOL2 WT mice." (PMID 38627980, 2024). "Bioluminescence imaging results showed that when the tumors in all of 6 control mice exhibited successful lung metastasis, the forced expression of OVOL2 completely suppressed this metastasis, whereas the size of the primary tumor was not significantly affected after 5 weeks." (PMID 28455959, 2017). "Ovol2KO tumor cells showed elevated FAO‐OCRs and ATP levels, indicating significantly enhanced FAO in the absence of OVOL2." (PMID 38627980, 2024).
OVOL2 also shares sentences with these, for which no sentence is quoted: ovarian carcinoma (4 papers); lung adenocarcinoma (2); actinic keratosis (1); Anaplastic Thyroid Cancer (1); Bowen’s disease (1); corneal disease (1); cutaneous squamous cell carcinoma (1); gastric cancer (1); Harboyan syndrome (1); Infertility (1); ischemic cardiomyopathies (1); liver cancer (1); osteosarcoma (1); pancreatic cancer (1); posterior polymorphous corneal dystrophy 1 (1); thymic hypoplasia (1).